IL6 (interleukin 6)
Diseases named in the same sentence as IL6 in open-access papers (continued):
Sharing a sentence is not in itself a finding about the gene and the disease.
tumor (continued). "Interestingly, ASK-1 inhibition reduces TLR-4-mediated inflammatory responses, including IL-6, IL-8, soluble VCAM, and G-CSF secretion from ECs, suggesting that EC-produced soluble immune mediators are involved in the regulating accessibility of immune cell types to tumor regions." (PMID 36901858, 2023). "In conclusion, we demonstrated that CAFs are the major regulators of IL-6 in the TME, and blood IL-6 concentration could be a potential biomarker of CAFs, while systemic administration of an anti-IL-6 receptor antibody overcomes CAF-induced immunosuppression and halts tumor progress." (PMID 36764954, 2023). "TNF-alpha signaling via NF-kB, IL6/JAK/STAT3 signaling, PI3K/AKT/mTOR signaling, MYC targets v2, TGF-beta signaling, and Kras signaling were mostly negatively correlated with LRRC3B expression, consistent with silencing of LRRC3B in tumor tissue, which may result in carcinogenesis." (PMID 36798137, 2023). "Prior studies have noted the ability of CAAs in secreting high abundance of IL-6, IL-1β, CCL2, chemokine (C–C motif) ligand 5 (CCL5), tumor necrosis factor-α (TNF-α), vascular endothelial growth factor (VEGF) and leptin, which could enhance tumor invasion and immune escape." (PMID 37127625, 2023). "Interestingly, several research groups have documented that lycopene could suppress proinflammatory cytokines such as IL-1, IL-1β, IL-6, and TNF-α in several tumor models, including PCa, by downregulating their production and, thus, preventing the inflammatory state." (PMID 36829848, 2023). "However, inflammatory cells produce tumor necrosis factor-α, transforming growth factor-β, interleukin-6 (IL-6), and other cytokines, which regulate the transcription factor NF-κB and the signal transducer and activator of transcription-3 (STAT3) pathways, and promote tumor cell metastasis." (PMID 36686786, 2022). "In addition to PD-L1, EVs transported to Mφs can promote the expression of cytokines IL-6, IL-10, and MCP-1 by activating the Janus kinase 2-signal transducer and activator of transcription 3 (JAK2/STAT3) pathway, leading to immunosuppression of Mφs and promotion of tumor development." (PMID 36032078, 2022). "However, HMGB1 could promote the release of cytokines such as IL-6 and IL-8 by activating MAPK- and MyD88-dependent NF-KB pathways in the extracellular matrix, thus stimulating tumor cell proliferation, angiogenesis, epithelial-mesenchymal transition (EMT), invasion, and metastasis." (PMID 35273678, 2022). "In culture, leptin and IL-6 produced by obese adipocytes induced activation, proliferation, and migration of endothelial cells through upregulation of VEGF and VEGFR-2, suggesting that adipocytes secrete multiple factors that could enhance angiogenesis within the tumor microenvironment." (PMID 35435599, 2022). "Our data showed that SUM149-derived IL-6 confers growth stimulation to SUM190 cells through a Tocilizumab-sensitive mechanism and suggests that this paracrine effect may sustain a long-term growth-promoting equilibrium between two such tumor cell clones in vivo." (PMID 35565421, 2022). "Notably, IKK inhibition had a greater effect than both TGFβR inhibition or TAK1 inhibition in reducing IL-6 loading into EVsMMA-MRC5, which also corresponded with a greater effect in suppressing the potency of EVsMMA-MRC5 for promoting EMT and drug resistance in A549 tumor cells." (PMID 36266345, 2022). "Furthermore, this metabolic dysregulation is also mediated by pro-inflammatory cytokines originated by tumor by-products, as well as by the host immune system, in which tumor necrosis factor (TNF-α), interferon-gamma (IFN-γ), and several interleukins, including IL-6, are involved." (PMID 35457471, 2022). "The infiltration of inflammatory cells and an environment enriched in various cytokines (TGF-β, IL-6, IL-10, granulocyte-macrophage colony-stimulating factor (GM-CSF), IL-1β, IL-23, and TNF-α) and chemokines (“chemotactic cytokines”) may be utilized by tumor cells." (PMID 36142391, 2022).
tumor (continued). "While 4T1-IL-6-KO tumor growth was similar to the control, the reduced IL-6 significantly expanded the total CD4+ Th population and Th17 in tumors, while Th22 and MDSC were reduced in all tissues; this suggests that clinical IL-6 depletion combined with immunotherapy could improve outcomes." (PMID 36142210, 2022). "In immune analysis, ICAM1, IL1B, IL-6, MMP1, MMP3, MMP9, and SERPINE1 all showed positive correlations with most immune cells, implying that CC and MF may exert an antitumor activity by interacting with these genes and immune cells, and thus control tumor development." (PMID 35783510, 2022). "In addition, the combination treatment also affected the anti-tumor immune response in other organs, as observed by a rise of the CD8+ and CD4+ T cells in the spleen, increasing the secretion of pro-inflammatory cytokine IL-12, and decreasing the secretion of pro-tumor inflammatory factor IL-6." (PMID 36329529, 2022). "We showed that the circCUL2/miR-203a-5p/MyD88/NF-κB/IL6 axis contributes to the induction of iCAFs and established a distinct fibroblast niche for PDAC progression, which could help the development of strategies that selectively target tumor-promoting CAFs in PDAC." (PMID 35189958, 2022). "The reason for this could be that the tumor inhibitor miR101 is disturbed in tumor-derived exosomes under hypoxic stress, leading to the upregulation of cyclin-dependent kinase 8 (CDK8) in macrophages and the stimulation of IL1A and IL6 secretion in macrophages." (PMID 36071472, 2022). "designed a CAR-T cell with a non-signaling membrane-bound IL-6 receptor (mbaIL-6) and found that mbaIL-6 expressed on the surface of T cells could rapidly remove IL-6 from the culture serum and circulation in a mouse model without affecting the anti-tumor potential of CAR-T cells." (PMID 36105799, 2022). "Such a result may be explained by the fact that MSCs play a supporting role in tumorigenesis through the secretion of factors such as IL6, IL8, VEGF, platelet-derived growth factor (PDGF), fibroblast growth factor (FGF)-7, TGF-β, and vimentin, supporting the growth and chemoresistance of the tumor." (PMID 36354566, 2022). "Moreover, IL-6, IL-10 and VEGF, produced by cancer cells, may activate STAT3 in a paracrine fashion in the cells present in the tumor microenvironment, such as myeloid cells or fibroblasts, transforming them into cells that support tumor growth." (PMID 33513694, 2021). "Drosophila cancer models may represent a suitable option for exploring the interplay between ROS, Upd/IL-6, and non-autonomous autophagy and understand how metabolic changes in the microenvironment and in distal tissues may affect tumor growth and shape responses in the host." (PMID 34831432, 2021). "Notably, ABR-238901, a small molecule that inhibits the interaction of S100A9 with its receptors, decreases the secretion of IL-6 and IL-10 from MDSCs, inhibits the neoangiogenic process, but would not have shown satisfactory efficacy in reducing tumour progression." (PMID 34445745, 2021). "According to this study, chemerin might suppress IL-6 and GM-CSF (Granulocyte-macrophage colony-stimulating factor) production, which results in impaired accumulation of myeloid-derived suppressor cells (MDSC) and formation of tumor-suppressing microenvironment with decreased angiogenesis." (PMID 34946244, 2021). "Importantly, IL-6 has been shown to be mostly expressed by the stroma and not by the tumor cells." (PMID 34203869, 2021). "Thus, IL-6 signaling deregulation is more likely a marker of overall sick social liaisons of the tumor microenvironment rather than a tool for the precise assessment of individual members of this ecosystem, which was also demonstrated for HNSCC in vitro and in clinical material." (PMID 34681685, 2021).
tumor (continued). "Interestingly, combined blockade of the mutually regulated immunosuppressive activities of IL-6 and PD-1/PD-L1 signals enhances expression of T-cell-attracting chemokines and exerts a synergistic antitumor effect, suggesting an IL6-PD1/PD-L1 cross-talk in the tumor microenvironment." (PMID 34018387, 2021). "Our work shows that hypoxia enhances IL-6-mediated CD40 expression in tumor Mφs, implicating that cancer therapy by modulation of tumor metabolism or normalization of blood vessels to relieve tumor hypoxia may need additional CD40 agonist treatment to stimulate anti-tumor immunity." (PMID 34103524, 2021). "In addition, Ciji-Hua’ai-Baosheng improved the immune function of H-22 tumor-bearing mice after treatment with chemotherapy and alleviated CTX-induced colitis, manifested as elevated lymphocytes in spleen, augmented IL-2, IFN-γ and TNF-α, and the reduced IL-6 in serum and tumor tissues." (PMID 34722304, 2021). "Interestingly, tumor location, alcohol consumption, physical activity, body mass index, as well as ethnicity, education and financial status had no relevant correlation with serum IL-6 levels." (PMID 34681685, 2021). "However, several pro-inflammatory cytokines, including IL-1β, IL-6, and IL-17, are blocked by infliximab stimulation or combined treatment of infliximab and TNF-α, which indicates that anti-TNF-α treatment might modulate tumor-influenced inflammation in HCC." (PMID 34948424, 2021). "Likewise, IL-6 and leptin derived from adipocytes could increase the PD-L1/NKG2D ligand level in cancer cells by activating the JAK/STAT3 signaling pathway, thereby decreasing the cytotoxicity of NK cells to tumor cells." (PMID 33413697, 2021). "Interestingly, ELAVL1 (HuR) was shown to modulate the expression of IL-5, IL-6, CCL-5, and TNF-alpha cytokines harboring the HuR-binding motif, which in consequence can influence the cross-talk between HRS cells and the immune infiltration in the tumor microenvironment." (PMID 33544339, 2021). "However, given the high heterogeneity of cells in tumor tissues, it is not clear here whether IL6 is secreted from tumor cells, BMSC, TAM, CAFs or other types of cells in the TME of NB." (PMID 34790130, 2021). "In addition to CAF-derived soluble factors CXCL12, IL-6, and TGF-β, CAFs also inhibit antitumor cytotoxicity of CD8+ T cells through the acquisition of immune checkpoint molecules, such as programmed cell death ligand 1 (PD-L1), PD-L2, and Fas ligand in several tumor types." (PMID 33673405, 2021). "Therefore, we believe the primary action of tumor-derived IL-17A in tumor-bearing mice is to induce a rapid expansion of myeloid cells, including neutrophils and MDSCs, via the production of STAT3-activating cytokines including IL-6, G-CSF, and GM-CSF by tumor cells." (PMID 32770025, 2020). "Additionally, tumor cells are capable of producing mediators of chronic inflammation, such as granulocyte-macrophage colony-stimulating factor (GM-CSF), vascular endothelial growth factor (VEGF), TNF-α, IL-1β, and IL-6, which induce the generation and expansion of MDSCs in situ." (PMID 33042814, 2020). "Regarding the myeloid compartment, increased IL-6 signaling could aid to enhance the expression of immunosuppressive arginase-1 or to diminish major histocompatibility complex II (MHCII) and CD80 expression in dendritic cells (DCs), thereby supporting tumor immune escape mechanisms." (PMID 32604862, 2020). "Notably, the IL6 and IL8 cytokine expression was downregulated in TAFs as compared to naive fibroblasts that was further corroborated by the expression analysis from the cellular mRNA and from whole tumour samples supporting their frequent downregulation in adenocarcinomas." (PMID 32341349, 2020). "In addition to VEGF, fibroblasts release various inflammatory cytokines such as interleukin 6 (IL-6) and transforming growth factor β1 (TGF-β1), to induce epithelial-mesenchymal transition (EMT) by increasing the expression of N-cadherin and vimentin in tumours." (PMID 32340319, 2020).
tumor (continued). "However, it seems that some of the well-defined proinflammatory cytokines such as TNFα, IL-1β, and IL-6 may not play the role as the expression of these cytokines were remarkably downregulated in tumor tissues." (PMID 32382012, 2020). "Therefore, administration of an anti-IL-6 therapy such as Tocilizumab to WM patients may provide therapeutic efficacy by targeting the TME to reduce IgM production and slow the rate of tumor growth." (PMID 31164961, 2019). "Moreover, a high proportion of CD204+/CD163+ macrophages, as well as increasing levels of IL-6, IL-10, VEGF, and MCP-1 secretion by GC-MSC-treated macrophages, synergistically revealed a potent role of GC-MSCs in polarizing macrophages into a pro-tumor (M2) phenotype." (PMID 31801938, 2019). "On the other hand, IL‐6 secreted by GBM acts on hepatocytes and may secrete high levels of CRP through the janus kinase‐signal transducer and activator of transcription (JAK‐STAT) pathway, which reaches the tumor site through blood circulation and then accumulates in tumor tissue." (PMID 31599129, 2019). "In addition, knockdown of LIF but not IL-6 impaired tumor initiation rate in xenograft models." (PMID 31296870, 2019). "Finally, MSCs are also implicated in the acquisition of chemoresistance via i) the release of soluble factors by MSCs (IL-6, IL-8, VEGF), ii) an exchange of membrane proteins between MSCs and tumor cells, iii) the release of exosomes, or iv) through the direct interaction within tumor cells." (PMID 31547627, 2019). "Furthermore, whether in patients with MVI or without MVI, or in patients with maximum tumor size > 5 cm or ≤5 cm, high preoperative serum IL6, IL8, and TNF-α levels were distinctly correlated with shorter RFS." (PMID 31781194, 2019). "Interestingly, the results showed that the IFNγ, TNFα, and IL-6 levels in the serum of the CAR-147 macrophage group were decreased compared with that of the control group, while the IL-12 and IFNγ levels were increased in tumour tissue samples from the CAR-147 macrophage-treated mice." (PMID 31570753, 2019). "However, recent studies have suggested that in various cancers, IL-6 may play a critical role in the communication between cancerous and non-cancerous cells within the tumor microenvironment." (PMID 30927911, 2019). "Furthermore, tumor-restraining CAF may increase antitumor immunity, by secretion of immunomodulatory cytokines such as IL-10, TNF, and IL-6, aiding in recruitment of macrophages and T lymphocytes, thus converting an immune-suppressive into immune-stimulating cancer microenvironment." (PMID 30871158, 2019). "Besides, DC cells activated with CD137 could not only secrete IL-2 and IL-6 to promote the proliferation of T cells but also activate cytotoxic lymphocytes (CTLs) and promote the secretion of IFN, hereby enhancing the anti-tumor effect." (PMID 31708918, 2019). "In addition to activating the JAK/STAT3 pathway via phosphorylation of STAT3, the IL-6/IL-6R interaction leads to low E-cadherin expression and high vimentin expression as well as upregulated expression of Snail, ZEB1, ZEB2, Twist and other transcription factors that promote tumor metastasis." (PMID 30157906, 2018). "Also, neither M(IL-6) cells nor SnMP treatment affected the permeability of the endothelial monolayer, suggesting that HO-1 plays an active role in the migration of the tumour cells through the endothelial cell layer." (PMID 30054470, 2018). "However, the patients with high STAT3 tumor had a significantly higher risk of both disease progression (p = 0.009) and cancer-specific mortality (p = 0.009), but not with tumors expressing S1PR1 or IL-6." (PMID 30091994, 2018). "EGF may also be involved in reducing docetaxel efficacy in cancer cells; however, a number of other molecules including IL-6, TGFβ, CXCL12, CCL21, VEGF, among others secreted by activated lymphatics are known contributors to drug resistance and these interactions may be tumor cell specific." (PMID 29976154, 2018).
tumor (continued). "Hence, even if targeting IL-6 in patients with GI cancer proves not to have any anti-tumor effect, the treatment may decrease severe cancer symptoms such as cachexia and fatigue, improving the patients’ quality-of-life." (PMID 30038723, 2018). "The poor clinical outcome associated with the BRD4+/high group in the absence of T-bet+ TILs suggests that BRD4 may promote tumor progression through upregulation of chronic inflammatory pathways marked by the production of proinflammatory cytokines such as IL-1α, IL-1β, and IL-6." (PMID 30029633, 2018). "Thus, we cannot exclude the possibility that most of the suggested biomarkers of PCNSL (such as IL-6, IL-10 and CXCL-13) and soluble receptor proteins (such as sCD27 and sIL-2R) were more abundant in PCNSL patients because they had originated in PCNSL tumor tissue." (PMID 29299134, 2017). "IHC analysis on type 1 EC showed that the selected adipokines are differently expressed within the tumor; staining could be located in the cytoplasm of EC cells (TNF α and RBP4), in the cytoplasm of stromal cells (adiponectin) or both in EC and stromal cells (IL-6 and SPARC)." (PMID 28505082, 2017). "Interestingly, IL-6 is also upregulated (fold change 7.317) in the combination group, and we found that IL-6 together with increased compressive force led to enhancement of positive feedback that controls EMT and tumor progression via the Akt/GSK-3β/β-catenin signaling pathway." (PMID 28846080, 2017). "Furthermore, Dub3-knockdown or WP1130 treatment significantly inhibited IL-6-mediated invasion of tumor cells; however, WP1130 could not suppress IL-6-induced invasion in Dub3-knockdown cells." (PMID 29088851, 2017). "Additionally, prolonged exposure of MCF cells to IL6 or IL8 induced the appearance of senescent cells, suggesting a mechanism by which senescence and inflammation are reinforced favouring the acquisition of EMT and stem-like features at the population level, thus increasing tumour aggressiveness." (PMID 28472950, 2017). "However, TNFα and IL-6 levels did not increase in TLR4−/− tumor-bearing mice." (PMID 28536426, 2017). "In addition, by in vivo studies, “tumour-educated” MSC (TEMSCs) injected in a pre-clinical mouse model supported OS growth and lung metastasis formation, while co-administration of tocilizumab, an interleukin-6 antibody, strongly reduced the effects induced by TEMSCs." (PMID 29246026, 2017). "It indicates that IL-6 may also regulate the process of EMT during the progression of NSCLC, by which cells change from a highly polarized epithelial phenotype with intact cell–cell junctions to a migratory mesenchymal phenotype to promote tumor cell metastasis." (PMID 27095254, 2016). "In agreement with the results of tumour growth, no remarkable induction of OVA-specific CD8+ T cells and their functional enhancement that was monitored by IFN-γ response were observed in aged mice transferred with IFN-γ-deficient OT-II cells, regardless of IL-6 blockade." (PMID 25850032, 2015). "Similarly, siRNA can induce a reactive inflammatory response, which likely explains the marginally higher distant tumor growth rate in the scrambled siRNA treatment arm (where there are no suppressive effects of the anti-IL6 siRNA) compared to even RF ablation alone." (PMID 26154425, 2015). "We also found increased IL-6 induction when EL4 cells were co-cultured with lymphocytes from intratumourally administered SZU-101-treated mice, suggesting that the intratumourally administered SZU-101 may have triggered an IL-6-based tumour-specific memory immune response." (PMID 25887995, 2015). "Thus, further translational study is envisioned defining the relevance of IL-6 and VEGF siRNA to other tumor types (including those with variable growth rates) and organs commonly ablated in clinical practice which may be more or less expressive of these cytokines." (PMID 26154425, 2015).